SNORA37 (small nucleolar RNA, H/ACA box 37)
Synonyms: ACA37
Gene: Small nucleolar RNA gene on chromosome 18 (54,222,284 to 54,222,412, reverse strand). Ensembl gene ENSG00000207233.
Gene Ontology:
Biological process: RNA processing
Cellular component: nucleolus
Homologues: Orthologues: chimpanzee SNORA37 (100% identical), macaque SNORA37 (98% identical). Paralogues in human: SNORA30B (93% identical), SNORA30 (85% identical).
Diseases named in the same sentence as SNORA37 in open-access papers:
SNORA37 is named in the same sentence as 3 diseases in open-access papers, as found by Europe PMC text mining. Sharing a sentence is not in itself a finding about the gene and the disease. The quoted sentences say what the papers report.
gastric cancer (1 paper, 2025). A primary or metastatic malignant neoplasm involving the stomach. "Gain- and loss-of-function studies indicated that SNORA37 promoted the growth, invasion, and metastasis of gastric cancer cells in vitro and in vivo." (PMID 39815331, 2025). "In clinical gastric cancer cases, high levels of SNORA37, CMTR1, ELAVL1, or CD44 were associated with shorter survival and poor outcomes of patients." (PMID 39815331, 2025). "In conclusion, we demonstrate, for the first time, that SNORA37 is up-regulated in gastric cancer tissues and associated with poor outcomes of patients." (PMID 39815331, 2025). "SNORA37, an ELAVL1-facilitated H/ACA box snoRNA derived from host gene MBD2, was up-regulated in gastric cancer tissues and associated with poor outcomes of patients." (PMID 39815331, 2025). "Collectively, these findings indicated that SNORA37 promoted tumorigenesis and aggressiveness of gastric cancer." (PMID 39815331, 2025). "SNORA37 directly binds to cap methyltransferase 1 (CMTR1) to facilitate its interaction with ELAVL1, resulting in nuclear retention and activity of ELAVL1 in regulating alternative splicing of CD44, which indicates the roles of SNORA37/CMTR1/ELAVL1 feedback loop in gastric cancer progression." (PMID 39815331, 2025). "In this study, we identify SNORA37 as an ELAVL1-generated 129-nt H/ACA box snoRNA derived from host gene methyl-CpG binding domain protein 2 (MBD2), which is associated with progression and worse outcomes of gastric cancer." (PMID 39815331, 2025). "In cultured gastric cancer cell lines (MKN-45, HGC-27, AGS, SNU-1), the expression of SNORA37 and SNORD33 was consistently enhanced than that of GES-1 cells." (PMID 39815331, 2025). "In addition, there was facilitated or reduced ELAVL1 enrichment on CD44 pre-mRNA in gastric cancer cells with stable over-expression or knockdown of CMTR1, while silencing or ectopic expression of SNORA37 abolished these effects." (PMID 39815331, 2025). "Moreover, silencing of ELAVL1 decreased the levels of SNORA37, without alteration of MBD2 expression, in gastric cancer cells." (PMID 39815331, 2025).
cancer (2 papers, 2021 to 2025). A tumor composed of atypical neoplastic, often pleomorphic cells that invade other tissues. "Since previous studies show that both CD44v6 and PRMT2γ play crucial roles in cancer pathogenesis, our findings indicated the oncogenic roles of SNORA37 via modulating alternative splicing of oncogenes." (PMID 39815331, 2025). "SNORA37 regulates cancer cell lipid synthesis by mediating histone modification." (PMID 34047477, 2021).
tumor (1 paper, 2025). "Stable over-expression of CMTR1 or ELAVL1 into HGC-27 cells resulted in increase of growth, tumor weight, CD31-positive microvessels, and Ki-67 proliferative index of subcutaneous xenografts formed in nude mice, accompanied by up-regulation of CD44v, which were prevented by knockdown of SNORA37." (PMID 39815331, 2025).